SNORA75B (small nucleolar RNA, H/ACA box 75B)
Gene: Small nucleolar RNA gene on chromosome 4 (17,320,746 to 17,320,882, reverse strand). Ensembl gene ENSG00000206780.
Gene Ontology:
Biological process: RNA processing
Cellular component: nucleolus
Homologues: Orthologues: chimpanzee SNORA75 (99% identical), macaque SNORA75 (97% identical), dog SNORA75 (87% identical), pig SNORA75 (83% identical), rat Snora75 (80% identical), mouse Gm25038 (76% identical), mouse Gm56482 (65% identical), zebrafish SNORA75 (64% identical), zebrafish SNORA75 (61% identical). Paralogues in human: SNORA75 (91% identical), SNORA75 (77% identical), SNORA75 (74% identical), SNORA75 (73% identical), SNORA75 (72% identical), SNORA75 (52% identical).